MIR3180-4 (microRNA 3180-4)
Synonyms: hsa-mir-3180-4; mir-3180-4
Gene: MicroRNA gene on chromosome 16 (15,154,850 to 15,155,002, reverse strand). Ensembl gene ENSG00000264115.
Gene Ontology:
Biological process: miRNA-mediated post-transcriptional gene silencing